PAK3 (p21 (RAC1) activated kinase 3)
Diseases named in the same sentence as PAK3 in open-access papers (continued):
Sharing a sentence is not in itself a finding about the gene and the disease.
cervical cancer (2 papers, 2015 to 2018). A primary or metastatic malignant neoplasm involving the cervix. "The authors found that the proliferation/viability of HPV+ cervical cancer cells, CaSki, HeLa and SiHa, was selectively inhibited by multiple PAK3 and SGK2 shRNAs." (PMID 25615606, 2015). "Nevertheless, the suggested importance of PAK3 or SGK2 in the survival of HPV+ cervical cancer cells elevated our interest in these kinases as potential targets for HPV drug intervention." (PMID 25615606, 2015). "In summary, we have validated the function of PAK3 and SGK2 lentiviral shRNAs in the knockdown of PAK3 and SGK2 gene expression, and also observed viability loss of HPV+ cervical cancer cells (HeLa and CaSki) mediated by the lentiviral shRNAs." (PMID 25615606, 2015). "PAK3 and SGK2 were recently associated with the survival of HPV+ cervical cancer cells." (PMID 25615606, 2015). "To determine whether HPV+ cervical cancer cells are specifically vulnerable to PAK3 and SGK2 shRNAs, we investigated four control lentivirus shRNA vectors that do not target human genes (Luc, EGFP, T-GFP and NT shRNAs) for their effect on the proliferation/ viability of HeLa and CaSki cells." (PMID 25615606, 2015). "It was proposed that the p21-activated kinase 3 (PAK3) and the serum and glucocorticoid-induced kinase 2 (SGK2) were essential for HPV positive (HPV+) cervical cancer cell survival." (PMID 25615606, 2015). "The p21-activated kinase 3 (PAK3) and the serum and glucocorticoid-induced kinase 2 (SGK2) have been previously proposed as essential kinases for human papillomavirus positive (HPV+) cervical cancer cell survival." (PMID 25615606, 2015). "We observed that the phenotypes of HPV+ cervical cancer cells induced by various PAK3 and SGK2 shRNAs could not be rescued by complement expression of respective cDNA constructs." (PMID 25615606, 2015). "In this study, we demonstrate that the phenotypes of HPV+ cervical cancer cells induced by PAK3 or SGK2 shRNAs could not be rescued by complement expression of respective cDNA constructs." (PMID 25615606, 2015). "Therefore, the lethality of PAK3 or SGK2 shRNAs to HPV+ cervical cancer cells did not appear related to the inhibition of PAK3 or SGK2 expression but rather through a non-specific RNAi effect." (PMID 25615606, 2015).
developmental delay (2 papers, 2020 to 2021). "We diagnosed two male siblings with developmental delays as having a PAK3 likely pathogenic variant." (PMID 32050918, 2020). "The PAK proteins, PAK1 and PAK3, are central regulators of neuronal development and activating PAK1 mutations were aetiologic for secondary macrocephaly, developmental delay, ataxic gait and seizures in two unrelated patients." (PMID 34111223, 2021).
gastric cancer (2 papers, 2020 to 2022). A primary or metastatic malignant neoplasm involving the stomach. "In this study, we found that PAK3 expression was aberrantly down-regulated in gastric cancer, and PAK3 participated in gastric cancer cell cycle arrest, apoptosis, cell proliferation and migration." (PMID 32742198, 2020). "Consistently, circ_0000190 overexpression increased apoptosis, decreased cell proliferation and migration of gastric cancer cells, which were inhibited after miR-1252 mimics transfection and then restored by further transfection with PAK3." (PMID 32742198, 2020). "Consistently, we also found that circ_0000190 overexpression significantly decreased miR-1252 level and increased PAK3 expression, while miR-1252 mimics significantly decreased PAK3 expression in gastric cancer cells." (PMID 32742198, 2020). "Functional and mechanistic analysis supported that circ_0000190 overexpression markedly decreased gastric cancer cell survival, growth and migration, which was achieved by directly targeting miR-1252/PAK3 axis." (PMID 32742198, 2020). "More importantly, we noted that circ_000190 acted as a sponge of miR-1252 and resultantly increased the expression of PAK3, eventually leading to decrease in cell proliferation and metastasis of gastric cancer cells." (PMID 32742198, 2020). "The immunofluorescence staining showed that PAK3 expression was significantly inhibited after miR-1252 mimics transfection, which could be reversed after additional transfection with PAK3 in gastric cancer cells." (PMID 32742198, 2020). "Overall, we revealed that circ_0000190/miR-1252/PAK3 may serve as a potential novel strategy for the treatment of gastric cancer." (PMID 32742198, 2020). "Next, we further explored the relation between miR-1252 and PAK3 in gastric cancer." (PMID 32742198, 2020). "We found that the cell viability was significantly increased by circ_0000190, and inhibited by addition of miR-1252 mimics, which could be abolished by further overexpression of PAK3 in gastric cancer cells." (PMID 32742198, 2020). "Moreover, We also found that the pro-apoptotic protein, caspase-3 was significantly increased by circ_0000190 transfection, and then suppressed by co-transfection of mimiR-1252, but restored by overexpression of PAK3 in gastric cancer cells." (PMID 32742198, 2020). "Circ_0000190 suppresses gastric cancer progression potentially via inhibiting miR-1252/PAK3 pathway, employing circ_0000190 might be a promising therapeutic strategy for the treatment of gastric cancer." (PMID 32742198, 2020). "Circ_0000190 inhibited gastric cancer cell viability, proliferation and migration, and induced apoptosis and cell cycle arrest by regulating the expression of capase-3, p27 and cyclin D. In addition, the circRNA was validated as a sponge of miR-1252, which directly targeted PAK3." (PMID 32742198, 2020). "However, there is no elucidation about the association between PAK3 and gastric cancer." (PMID 32742198, 2020).
hepatocellular carcinoma (2 papers, 2022 to 2024). A malignant tumor that arises from hepatocytes. "Moreover, PAK3 gene expression is higher in hepatocellular carcinoma patients and has positive correlation with tumor stage and grade." (PMID 37505298, 2024). "There is a member of the PAK family, P21-activated kinase 3 (PAK3), a serine or threonine protein kinase, that could achieve Epithelial–mesenchymal transition (EMT) of hepatocellular carcinoma by regulating Smad2 and Smad3." (PMID 37505298, 2024). "When PAK3 was overexpressed in Huh7 and HepG2 hepatoma cells, the levels of p-Smad2 and p-Smad3 were significantly increased, while the levels of total Smad2 and Smad3 were almost unchanged, suggesting that PAK3 may act through the Smad-dependent TGF-β pathway to promote EMT in hepatoma cells." (PMID 34976179, 2022).
HIV-1 infection (2 papers, 2013 to 2023). The type species of lentivirus and the etiologic agent of acquired immunodeficiency syndrome (AIDS). "Furthermore, it has been shown that the depletion of PAK1, and to a lesser extent of PAK3, blocks HIV-1 infection in Jurkat cells." (PMID 36622146, 2023). "In addition, an RNAi screen identified Pak1 and Pak3 to be important host factors that support HIV-1 infection in HeLa cells and T lymphocytes." (PMID 23622267, 2013).
malignant melanoma (2 papers, 2015 to 2016). "For example, mutations in malignant melanoma are predicted to disable the RAC1-DOCK1 interface but enable interactions between RAC1 and PAK3." (PMID 27698488, 2016).
schizophrenia (2 papers, 2017 to 2022). A major psychotic disorder characterized by abnormalities in the perception or expression of reality. "Git1 point mutations associated with schizophrenia show defects in PAK3 (p21 protein (Cdc42/Rac)-activated kinase 3) and MAPK (mitogen-activated protein kinase) activation and signaling." (PMID 29150658, 2017). "Most schizophrenia cases carrying GIT1 variants fail to induce PAK3 activation and GAD1, the key enzyme in GABA biosynthesis, in neurons, suggesting the contribution of PAK3 dysregulation in the synaptic deficits in schizophrenia." (PMID 33306168, 2022).
adenoma (1 paper, 2025). A neoplasm arising from the epithelium. "A Pak3High cluster (Pak3; P21 Rac1/CDC42 activated kinase 3) was the most enriched in Smad4fl/fl (10.5%) compared to Smad4+/+ (2.5%) control adenoma." (PMID 40348815, 2025). "Despite the correlation established for Spp1 and Pak3 in mouse adenoma organoids, these two genes did not appear significantly differentially expressed in human colorectal cancer with respect to SMAD4 variants." (PMID 40348815, 2025). "The same comparison in adenoma organoids between genotypes and all timepoints post TGF-β1 showed a non-significant difference in expression of Pak3, suggesting this was an in vivo adaptation that was not reproduced in organoids." (PMID 40348815, 2025).
autism (1 paper, 2021). Persistent deficits in social interaction and communication and interaction as well as a markedly restricted repertoire of activity and interest as well as repetitive patterns of behavior. "Moreover, the candidate genes PAK3, OCRL, DCX, PTK2, KCNQ3, SOX3, and LAMA1 were associated with autism, brain disease, Dent disease, and other conditions that present ID as a hallmark, corroborating our findings." (PMID 33922640, 2021).
autism spectrum disorder (1 paper, 2009). A spectrum of developmental disorders that includes autism, and Asperger syndrome. "Given the link between another small GTPase-dependent kinase, PAK3, and mental retardation, our results suggest that MRCKγ could participate in the signaling pathways involved in mental retardation and autism spectrum disorders." (PMID 19402746, 2009).
B-cell Lymphoma (1 paper, 2025). "Key genes such as PAK3, LINC00487, AID, PURPL, and BCL2 were among the most dysregulated, highlighting TIMAP’s role in critical oncogenic pathways in B-cell Lymphoma." (PMID 41170526, 2025).
colorectal cancer (1 paper, 2025). A primary or metastatic malignant neoplasm that affects the colon or rectum. "SMAD4, ID1, SPP1 and PAK3 mRNA expression also appeared to have prognostic implications for colorectal cancer using the TCGA cohorts, and with further evaluation required in extended human cohorts, are candidate functional readouts associated with disruption of the TGF-β-BMP-SMAD4 pathway." (PMID 40348815, 2025).
fragile X syndrome (1 paper, 2023). A genetic syndrome caused by mutations in the FMR1 gene which is responsible for the expression of the fragile X mental retardation 1 protein. "First evidence of this concept is that the expression of an autoinhibitory domain of PAK3, which targets all three group I PAKs improves the cellular and behavioral phenotype of Fmr1 KO mice, a model of Fragile X syndrome." (PMID 36937657, 2023). "Furthermore, PAK1, but not PAK2 nor PAK3, interacts with FRX family proteins involved in Fragile X syndrome, notably by phosphorylating FRX1 at Ser-420." (PMID 36937657, 2023).
Immunodeficiency (1 paper, 2022). Failure of the immune system to protect the body adequately from infection, due to the absence or insufficiency of some component process or substance. "On the other hand, PAK2 interacting partners such as ARHGEF7, also known as PAK3 (a positive regulator of apoptosis) and Lymphocyte cytosolic protein 2 (LCP2), have been previously linked to human immunodeficiency." (PMID 35783297, 2022).
Macrocephaly (1 paper, 2023). Occipitofrontal (head) circumference greater than 97th centile compared to appropriate, age matched, sex-matched normal standards. "It was the first time macrocephaly was associated with PAK3 mutations." (PMID 36937657, 2023).
memory impairment (1 paper, 2017). "For example, DISC1 (Disrupted in Schizophrenia) regulates dendritic spine morphology via Rac1 and mutations in the cofilin kinase PAK3 lead to X-linked mental retardation and memory impairments." (PMID 28912711, 2017).
meningioma (1 paper, 2015). A generally slow growing tumor attached to the dura mater. "We found that Pak1 and Pak2 were much more abundant than Pak3 in both meningioma and arachnoidal cells, as determined by immunoblot." (PMID 25596744, 2015).
neuroendocrine tumors (1 paper, 2021). "PAK3 currently has been found to be overexpressed in neuroendocrine tumors." (PMID 34307365, 2021).
papillary carcinoma (1 paper, 2022). A malignant epithelial neoplasm characterized by a papillary growth pattern. "ERBB3/ERBB4/RAF1 kinases were activated in papillary carcinoma compared to other variants, PAK3/PAK6/CDK1 kinases were activated in NOS, and PRKACA/PRKACB/PRKACG kinases were activated in differentiation variants." (PMID 35659036, 2022).
renal cell carcinoma (1 paper, 2020). "The NR5A1-derived tumors showed 657 unique proteins that participate in Renal cell carcinoma (CRK, ELOB and PAK3) and Homologous recombination (ATM, BRCC3 and MRE11) among others." (PMID 33261069, 2020).
small cell lung carcinoma (1 paper, 2015). Small cell lung cancer (SCLC) is a highly aggressive malignant neoplasm, accounting for 10-15% of lung cancer cases, characterized byrapid growth, and early metastasis. "Since PAK3 protein is expressed at very low levels in HeLa and CaSki cells, and migrates with PAK2, which can also be detected by the N-19 PAK3 antibody, PAK3 protein knockdown was examined in a PAK3 high expression small cell lung carcinoma cell, DMS-79." (PMID 25615606, 2015).
tauopathy (1 paper, 2021). Neurodegenerative disorders involving deposition of abnormal tau protein isoforms (tau proteins) in neurons and glial cells in the brain. "Problem 2 asked participants to predict compounds that bind the Tauopathy pro-targets AURKA, PAK1, FGFR1, and STK11 and avoid the Tauopathy anti-targets PAK3, MAP3K7, and PIK3CA." (PMID 34520464, 2021). "Problem 2 asked participants to predict compounds that bound the Tauopathy pro-targets, AURKA, PAK1, FGFR1, and STK11 and did not bind PAK3, MAP3K7, and PIK3CA." (PMID 34520464, 2021).
type 2 diabetes (1 paper, 2021). "PAK3, CD44, CD5, SOCS3, VAV1, and PIK3CD are negatively correlated with cardiac systolic function, and P2RY1 is positively correlated with LVEF, which may be referred to in studies on type 2 diabetes." (PMID 34925642, 2021).
cancer (20 papers, 2012 to 2025). A tumor composed of atypical neoplastic, often pleomorphic cells that invade other tissues. "The aim of this study was to investigate the regulation of PAK3 expression by AP-1 and determine the effect of inhibiting PAK3 expression on cancer cell biology associated with AP-1 transformation." (PMID 23818969, 2013). "While there is limited reports showing PAK3 expression in cancers, PAK1 over-expression has been linked to ovarian, breast, bladder and lymph cancers, while elevated PAK2, PAK4 and PAK6 expression has also been observed in prostate cancer." (PMID 23818969, 2013). "Pak3 is a well-known downstream effector of Cdc42 and Rac1 GTPases that mediates motility and MAPK activation associated with cancer invasion and metastasis." (PMID 40348815, 2025). "Among the cancer genes involving cell motility, PAK3 was the top DEG after ablation of Smad4 (SPK vs. PK)." (PMID 34381046, 2021). "Problem 1 asked teams to predict molecules that bound the RETM955T-associated cancer targets RET[M918T], BRAF, SRC, S6K, and avoided binding to MKNK1, TTK, ERK8, PDK1, and PAK3." (PMID 34520464, 2021). "PAK3 has been implicated in a variety of pathological disorders and over-expression of other PAK-family members has been linked to cancer." (PMID 23818969, 2013). "Cancer-specific methylation of activated kinase 3 (PAK3) was found in several neoplasms, including OC with high frequency." (PMID 24086249, 2013). "Similarly, Mitogen-Activated Protein Kinase 4 (MAPK4) in 12 cancers, Serine/Threonine Kinase 32A (STK32A) and P21 (RAC1) Activated Kinase 3 (PAK3) in 10 cancers were found to be commonly downregulated." (PMID 33801837, 2021). "Drosophila Pak3 bears considerable amino acid identity and functional correspondence to the vertebrate group 1 Paks, which are extensively studied for their roles in several cancers and actively targeted in drug development." (PMID 33013303, 2020). "However, there is little research on the role of PAK3 in the development of cancer." (PMID 34976179, 2022). "These miRNAs bind directly to PAK3, blocking its production, and thus SMAD4 deletion activates the PAK3-JNK-Jun pathway, which in turn accelerates cancer metastasis." (PMID 37685308, 2023). "Accumulating data show that PAK1, PAK3, and PAK4 regulate cell proliferation, motility, and angiogenesis in several types of cancer cells." (PMID 31658701, 2019). "In vivo, as clearly shown, cancer cells metastasized in the lungs of the PAK3 overexpression group, but no metastasis was observed in the control group, which indicates that overexpression of PAK3 significantly promotes tumor metastasis." (PMID 34976179, 2022). "Problem 1 asked participants to predict molecules that bound the RETM955T-associated cancer pro-targets RET[M918T], BRAF, SRC, S6K, and did not bind the anti-targets MKNK1, TTK, ERK8, PDK1, and PAK3." (PMID 34520464, 2021). "On the other hand, looking at studies on cancer stem cells, one could agree that p21 plays an important role in inducing stemness, especially through p21 activated kinases (PAK1, PAK3, and PAK4)." (PMID 31416295, 2019). "In contrast, PAK3, PAK5, and PAK6 showed fewer alterations and did not exhibit strong associations with clinical outcomes in most cancer types, suggesting that their roles may be more tissue‐specific or context‐dependent." (PMID 39756822, 2025).